CDH23 (cadherin related 23)
Description:
Cadherins are calcium-dependent cell adhesion proteins. They preferentially interact with themselves in a homophilic manner in connecting cells. CDH23 is required for establishing and/or maintaining the proper organization of the stereocilia bundle of hair cells in the cochlea and the vestibule during late embryonic/early postnatal development. It is part of the functional network formed by USH1C, USH1G, CDH23 and MYO7A that mediates mechanotransduction in cochlear hair cells. Required for normal hearing.
Synonyms: CDHR23; PITA5; USH1D; formerly DFNB12
Tractability: Antibody: UniProt places it where antibodies can reach, with high confidence; UniProt predicts a signal peptide or a membrane-spanning region; its Gene Ontology location is reachable by antibodies, with medium confidence. PROTAC: ubiquitination databases record sites on it.
Gene: Protein-coding gene on chromosome 10 (71,396,920 to 71,815,947, forward strand). Ensembl gene ENSG00000107736.
Subcellular location: Cell membrane
Pathways (Reactome):
Sensory Perception: Sensory processing of sound by inner hair cells of the cochlea; Sensory processing of sound by outer hair cells of the cochlea
Gene Ontology:
Molecular function: identical protein binding; protein binding; beta-catenin binding; cadherin binding; calcium ion binding
Biological process: calcium ion transport; equilibrioception; photoreceptor cell maintenance; regulation of cytosolic calcium ion concentration; sensory perception of light stimulus; sensory perception of sound; calcium-dependent cell-cell adhesion; cell migration; cell-cell adhesion; neuron projection development; cell adhesion; homophilic cell-cell adhesion
Cellular component: catenin complex; membrane; stereocilium; plasma membrane
Genetic constraint (gnomAD): Loss-of-function variants: 179 observed, 295.95 expected, observed/expected ratio (o/e) 0.6, 90% interval 0.54 to 0.69. The upper end of that interval is the gene's LOEUF score, 0.69, which puts it in group 2 of 6, group 1 being the genes least tolerant of losing a copy. Missense variants: 4,320 observed, 4,620 expected, observed/expected ratio (o/e) 0.94, 90% interval 0.91 to 0.96. Synonymous variants: 1,819 observed, 1,890.3 expected, observed/expected ratio (o/e) 0.96, 90% interval 0.93 to 1.
Gene-disease validity (ClinGen):
ClinGen rates the evidence that CDH23 causes each of these diseases.
nonsyndromic genetic hearing loss (autosomal recessive): Definitive. A disease characterized by hearing loss that is not part of a larger syndrome.
Usher syndrome type 1 (autosomal recessive): Definitive. A syndrome characterized by congenital, bilateral, severe sensorineural hearing loss, abnormalities in the vestibular system, and adolescent-onset retinitis pigmentosa.
Homologues: Orthologues: chimpanzee CDH23 (99% identical), macaque CDH23 (98% identical), dog CDH23 (95% identical), guinea pig CDH23 (95% identical), rat Cdh23 (95% identical), mouse Cdh23 (94% identical), rabbit CDH23 (93% identical), zebrafish cdh23 (58% identical). Paralogues in human: DCHS1 (25% identical), DCHS2 (24% identical), PCDH7 (9% identical), CDHR2 (8% identical), PCDH1 (8% identical), CDH4 (8% identical), CDH2 (8% identical), CDH1 (8% identical), PCDH9 (7% identical), CDH3 (7% identical), PCDH11X (7% identical), CDH7 (7% identical), and 21 more.
Diseases named in the same sentence as CDH23 in open-access papers:
CDH23 is named in the same sentence as 97 diseases in open-access papers, as found by Europe PMC text mining. Sharing a sentence is not in itself a finding about the gene and the disease. The quoted sentences say what the papers report.
Usher syndrome (90 papers, 2009 to 2025). A syndromic diseae characterized by the association of sensorineural deafness (usually congenital) with retinitis pigmentosa and progressive vision loss. "Mutations in the pathogenic gene CDH23 are known to cause Usher syndrome, affecting both auditory and visual functions." (PMID 40429749, 2025). "Defective myo7a and cdh23, to a lesser extent, cause Usher Syndrome Type 1B (USH1B), which is characterized by deafness and reduced vestibular function." (PMID 40463242, 2025). "A similar situation was reported for CDH23-associated HL, which is caused by ARNSHL (DFNB12) or Usher syndrome (USH1D)." (PMID 38594301, 2024). "Genetic variants of the CDH23 gene have been linked to Usher syndrome type 1D (USH1D) and non-syndromic HL." (PMID 38410152, 2024). "In contrast, protein-truncating-related CDH23 mutations due to frameshift, splice site, or nonsense pathogenic variants are causative of the Usher syndrome with more severe phenotypes." (PMID 36468022, 2022). "Recessive mutations in Cdh23 are associated with Usher syndrome type 1d in humans, whose symptoms include congenital hearing loss." (PMID 35473764, 2022). "The CDH23 gene is known to cause either Usher syndrome type 1D (USH1D) or non-syndromic HL (DFNB12)." (PMID 34824372, 2022). "Three patients had hearing loss and were diagnosed with Usher syndrome, and they independently carried CDH23, PCDH15, and USH1G variants." (PMID 34721897, 2021). "Zebrafish studies have suggested that ER stress is a proximal cause of the death of hair cells carrying gene mutations linked to the Usher syndrome, such as the Cdh23 mutation." (PMID 32029702, 2020). "Biallelic variants in CDH23 are a frequent cause of both nonsyndromic HL (DFNB12) as well as Usher syndrome type 1, an autosomal recessive disorder characterized by prelingual HL, vestibular areflexia, and progressive retinitis pigmentosa." (PMID 32842620, 2020). "Homozygous mutations in CDH23 result in Usher syndrome, characterized by congenital sensorineural hearing loss, vestibular dysfunction and early-onset retinitis pigmentosa." (PMID 32201880, 2020). "Mutations in the CDH23 gene are known to cause both Usher syndrome type 1D (USH1D) and nonsyndromic hearing loss (DFNB12)." (PMID 32864763, 2020). "After WES analysis and prioritization of genetic variants, two nucleotide variants were identified in the CDH23 gene: c.6050-9G>A (already reported as pathogenic in an Usher syndrome patient) and c.6050-15G>A (novel)." (PMID 31546658, 2019). "It is noteworthy though, that analysis restricted to genes known to be associated with Usher syndrome based on the clinical symptoms would have revealed only the CDH23 variants while the EYS variants would have remained undetected." (PMID 30718709, 2019). "Mutations in CDH23 lead to two types of phenotypic disorder or nonsense, splice-site, frameshift mutations, which are assumed to severely disrupt the functions of cadherin 23, usually associated with Usher syndrome type 1D (USH1D; MIM601067)." (PMID 26264712, 2015). "The variant list derived from case 1024 (a male) highlighted two heterozygous missense variants in CDH23 as possible candidates even though recessive mutations in this gene usually cause Usher syndrome." (PMID 25133751, 2014). "Mutations in Usher syndrome-related genes were detected in three families, including one double heterozygous mutation of CDH23 and PCDH15." (PMID 24164807, 2013). "Mutations in the Cadherin 23 gene (CDH23) have been associated with Usher syndrome type 1D, and DFNB12, a form of autosomal recessive hearing loss." (PMID 21119891, 2010). "Given that cdh23 loss causes Usher syndrome, an autosomal recessive genetic disorder characterized by both hearing loss and retinal pigment degeneration, we wondered whether the downstream effects following from the loss of cdh23 led to visual impairment." (PMID 40429749, 2025).
Usher syndrome (continued). "Our constructed ABE cassette can also be used for the treatment of large genes that cannot be loaded into an AAV, such as CDH23, which is the causative gene of juvenile-onset bilateral sensorineural hearing loss, and Usher syndrome–related genes, by recombining the sgRNA of ABE." (PMID 40059830, 2025). "Alterations in CDH23 expression or function may lead to congenital deafness (Usher syndrome) and predisposition to schizophrenia." (PMID 38699454, 2024). "Potential causative variants were identified in genes associated with nonsyndromic hearing loss (CIB2, COL11A1, ILDR1, MYO15A, TMPRSS3, and WFS1), nonsyndromic hearing loss or Usher syndrome (CDH23, MYO7A, PCDH15, and USH2A), and other syndromic forms of hearing loss (CHD7, OPA1, and SPTLC1)." (PMID 34837038, 2022). "PCDH15 and CDH23 are the pathogenic genes for Usher syndrome." (PMID 36568381, 2022). "Most of the CDH23 variants are associated with Usher syndrome type 1 or syndromic deafness (USH1D)." (PMID 36468022, 2022). "Specifically, clinical investigation is required to determine whether pituitary MRI scans should be adopted in the screening of CDH23-related diseases, including Usher syndrome and age-related hearing loss." (PMID 36359740, 2022). "Similarly, genetic variants in CDH23 are also commonly found in cases of Usher syndrome, a deaf–blindness disorder." (PMID 34946889, 2021). "In this study, we report a pathogenic variant CDH23:p.Arg1746Gln in a case of congenital hearing loss with mild pigmentary changes in the retina, indicative of Usher syndrome, and a missense variant reported as likely pathogenic for MPS VI identified through whole exome sequencing (WES)." (PMID 35186827, 2021). "In particular, three genes implicated in Type 1 Usher syndrome (CDH23, MYO7A and USH1C), while selected for the resequencing arrays, were not incorporated in the HHL APEX array; a separate APEX array for this group of disorders was already available when the HHL APEX array was originally designed." (PMID 20668687, 2010). "Recessive mutations of the CDH23 gene (OMIM: 605,516) are responsible for both nonsyndromic deafness 12 (DFNB12, OMIM: 601,386) and Usher syndrome type 1D (USH1D, OMIM: 601,067)." (PMID 39777619, 2025). "Five patients had obtained a molecular genetic diagnosis of Usher syndrome (CDH23, n = 2; PCDH15, n = 1; USH2A, n = 2) from a genetic screen for early sensorineuronal hearing loss." (PMID 39596324, 2024). "Whilst suitable for a number of ciliopathy-related genes, such as RPGR (3.5 kb), many genes are beyond this capacity, including CEP290 (7.4 kb) and several of the Usher-syndrome-associated genes (MYO7A: 6.6 kb, CDH23: 10 kb, ADGRV1: 18.9 kb, USH2A: 15.6 kb)." (PMID 38474133, 2024). "Targeted exome sequencing identified four distinct genotypes and likely pathogenic sequence variants in cell lines derived from clinically diagnosed Usher syndrome patients: MY07A, CDH23, USH2A, and CLRN1." (PMID 39337481, 2024). "CDH23 is located on chromosome 10q21.1 and is in the MYP15 region of the HM locus, like PCDH15, which is also associated with Usher syndrome and retinitis pigmentosa." (PMID 37884635, 2023). "CDH23 has been implicated in ARNSHI and Usher syndrome type 1D 20, and was reported as an important contributor to HI in several global populations with high frequencies in Eastern Asian countries such as Japan41 and Korea42." (PMID 35440622, 2022). "PCDH15, CDH23 and MYO7A: While these three genes are known for Usher syndrome, they have AR nonsyndromic forms of hearing loss." (PMID 33924653, 2021). "The remaining three solved cases suffered from Usher syndrome due to putative pathogenic variants in ADGRV1, CDH23 and USH2A, one family for each gene." (PMID 33297549, 2020). "Mutation in CDH23 can lead to both NSHL (DFNB12) and Usher syndrome, characterized by congenital HL and RP." (PMID 33095980, 2020).
Usher syndrome (continued). "Recessive mutations of the CDH23 gene (MIM#605516) are responsible for both nonsyndromic deafness 12 (DFNB12, MIM#601386) and Usher syndrome type 1D (USH1D, MIM#601067)." (PMID 33316915, 2020). "Studies revealed that a defective CDH23 gene plays an important role in developing Usher syndrome (OMIM #601067) where it accounts for up to 32% of USH1 cases." (PMID 32115674, 2020). "Currently, up to 13 genes have been associated with Usher syndrome: MYO7A, USH1C, CDH23, PCDH15, USH1G, and CIB2 are responsible for USH1, although the role of CIB2 in the Usher syndrome has recently been put on doubt." (PMID 31231422, 2019). "Families 5, 6, and 7 appeared to have candidate mutations or variants in MYO7A, CDH23, PCDH15, and USH2A, all of which are associated with Usher syndrome." (PMID 24164807, 2013). "Mutations in CDH23, PCDH15, VLGR1 and clarin-1 cause Usher syndrome, characterized by congenital deafness, vestibular dysfunction and retinitis pigmentosa." (PMID 22363448, 2012). "Genetic counseling prior to analysis of genes potentially revealing Usher syndrome (CDH23, PCDH15 and MYO7A) is important and this should be explained to parents who agree to have this type of diagnostics performed for their child." (PMID 22607986, 2012). "CDH23 interacts with PCDH15 in the tip links of inner hair cells, and digenic interactions have been observed in both mice and humans, suggesting possible modification among genes associated with Usher syndrome." (PMID 40486680, 2025). "Mutations in CDH23 were found to cause Usher syndrome type 1D (USH1D) and nonsyndromic deafness DFNB12, while mutations in PCDH15 were associated with Usher syndrome type 1F (USH1F) and nonsyndromic deafness DFNB23." (PMID 40943399, 2025). "Given the association of various CDH23 mutations with usher syndrome, the patient underwent a thorough examination to rule out related phenotypes." (PMID 39777619, 2025). "Furthermore, the CDH23 gene is recognized as the gene responsible for autosomal recessive (AR) or digenic recessive Usher syndrome, specifically type 1D, in these individuals." (PMID 38785568, 2024). "Cadherin 23 (Cdh23) protein is localized to the upper part of the tip link in hair cells, and in humans, Cdh23 mutations cause nonsyndromic autosomal recessive deafness (DFNB12) and Usher syndrome type 1D." (PMID 32527008, 2020). "Among these genes is cadherin-related 23 (CDH23), causing Usher syndrome type 1D (USH1D)." (PMID 32115674, 2020). "That study allowed the identification of the CDH23 gene as responsible of Usher syndrome type 1." (PMID 31231422, 2019). "In this study, we identified two CDH23 noncanonical splice site (NCSS) variants in an Usher syndrome patient, one of them being novel (c.6050-15G>A)." (PMID 31546658, 2019). "This strategy would still not suffice for treatment of IRDs such as Usher syndrome type 1D or Alström syndrome type I (ALMS) due to mutations in CDH23 or ALMS1, respectively." (PMID 29292161, 2018). "Usher syndrome is heterogenous, both in terms of clinical presentation and genetic origin, with a number of diverse genes known to carry pathogenic mutations (Type 1: MYO7A, USH1C, PCDH15, CDH23, USH1G, and CIB2; Type 2: USH2A, ADGRV1, and WHRN; Type 3: CLRN1)." (PMID 38474133, 2024). "Notably, Müller glial cells also expressed the other USH1-associated genes USH1G, USH1C, CDH23, and CIB2, suggesting that Müller glial cells may be more mechanistically relevant to Usher syndrome pathology than previously considered." (PMID 38474133, 2024). "Usher syndrome type 1D could not be confirmed in this family inheriting CDH23 biallelic pathogenic variants, also responsible for DFNB12." (PMID 37811145, 2023). "This includes a variant of unknown significance (VUS) in CDH23 (c.5653CT), previously reported as a VUS in a case with Usher Syndrome, and a ClinVar reported pathogenic variant in NDUFAF3 (c.188dupA), a gene associated with Mitochondrial complex I deficiency, nuclear type 18." (PMID 34828371, 2021).
Usher syndrome (continued). "This study also describes 2 (out of 125) sporadic pituitary tumor patients with homozygous CDH23 variants, but it is not specified whether these individuals showed clinical manifestations of Usher syndrome." (PMID 32201880, 2020). "Correction of the auditory phenotype in C57BL/6N mice via CRISPR/Cas9-mediated homology-directed repair in the mouse Cdh23 gene, indicating that the CRISPR editing system has a potential for treating Usher syndrome." (PMID 32425987, 2020). "The recessive nature of CDH23, a gene related to Usher Syndrome, along with the lack of audiometric anomalies, rendered the existing evidence inadequate to substantiate a modifier impact." (PMID 41300751, 2025). "Mutations in the CDH23 gene can result in various conditions, including non-syndromic hearing loss (DFNB12), Usher syndrome type 1D, and age-related retinal degeneration." (PMID 39596651, 2024). "Unlike CDH23 and PDZD7, which cause non-syndromic hearing loss or Usher syndrome presenting as non-syndromic hearing loss during childhood, PTPN11 is associated with NS1, which shows a variety of phenotypes in multiple organs." (PMID 35248088, 2022). "CDH23 is responsible for both Usher syndrome and DFNB12 nonsyndromic deafness." (PMID 34997062, 2022). "One patient was found to be compound heterozygous for mutations in two different genes, one in PCDH15 and the other in CDH23; since proteins interact with one another and form dynamic protein complexes, digenic or oligogenic inheritance of Usher syndrome is not surprising." (PMID 21738395, 2011).